IL23R (interleukin 23 receptor)
Diseases named in the same sentence as IL23R in open-access papers (continued):
Sharing a sentence is not in itself a finding about the gene and the disease.
Candida infections (2 papers, 2019 to 2025). "Through in‐depth immunophenotyping and functional assays, we reveal the association between homozygous carriage of the common p.R381Q IL‐23R genetic variant and increased candidiasis susceptibility, relying on disrupted IL‐23‐mediated IL‐17 immunity." (PMID 40685773, 2025). "In this report, we reveal, for the first time, the association between homozygous carriage of the hypomorphic loss‐of‐function R381Q IL23R variant and susceptibility to candidiasis." (PMID 40685773, 2025). "We hypothesize that this is due to a lack of investigation in CMC cohorts, or a more subtle phenotype, and that the homozygous R381Q IL23R variant acts as a genetic risk factor for Candida infections." (PMID 40685773, 2025). "Here, we studied a homozygous carrier of the R381Q IL23R variant suffering from CMC and investigated the hypothesis of this variant acting as a genetic risk factor for Candida infection." (PMID 40685773, 2025). "Consistent with this, we detected IL-23R transcripts in some but not all of the myeloid cell subsets that succumbed to death during systemic candidiasis in absence of IL-23." (PMID 31887131, 2019).
Chronic Lymphocytic Leukemia (2 papers, 2024 to 2026). "It would appear that the anti-inflammatory effect of miR-146b-5p on IL-23R expression in chronic lymphocytic leukemia cells is mediated through the downregulation of the IL-12Rβ1 chain." (PMID 39796684, 2024). "Furthermore, studies have demonstrated that the IL-23R chain is present in chronic lymphocytic leukemia (B cells), with a positive correlation observed between this and tumor progression." (PMID 39796684, 2024).
Esophagus carcinoma (2 papers, 2014 to 2018). "Distribution of genotypes of IL-23R gene and associations with the risk of Esophagus carcinoma." (PMID 24586528, 2014).
fungal infections (2 papers, 2016 to 2020). "In fact, genetic variants in the IL23R gene have been associated with different susceptibility to fungal infections and IL-23R deficient mouse was susceptible to systemic infection with C. albicans." (PMID 33499953, 2020). "Th17 cells defend the body from extracellular bacterial and fungal infections, express the transcription factor RORC, the IL-23 receptor (IL-23R), the chemokine receptor CCR6, and the lectin receptor CD161." (PMID 27123929, 2016).
gastritis (2 papers, 2024 to 2025). Inflammation of the stomach. "In Helicobacter Pylori associated gastritis an increased IL-23R expression was found." (PMID 40297579, 2025). "One study demonstrated that the IL-23R+2199A/C polymorphism does not influence the mucosal cytokine profile in Iranian patients with H. pylori-associated gastritis." (PMID 39796684, 2024). "However, the same polymorphism (2199A/C) has been shown to alter the mucosal expression pattern of IL-23/IL-23R in patients with gastritis in the absence of H. pylori." (PMID 39796684, 2024).
glioma (2 papers, 2021 to 2025). A benign or malignant brain and spinal cord tumor that arises from glial cells (astrocytes, oligodendrocytes, ependymal cells). "Silencing of NAV3 in vitro also leads to upregulation of IL-23R in colorectal and glioma cell lines, linked to proinflammatory JAK-STAT signaling." (PMID 34298611, 2021).
Hashimoto thyroiditis (2 papers, 2021 to 2024). An autoimmune disorder caused by the production of autoantibodies against thyroid tissue. "Our previous study also confirmed that elevated miR-326 levels regulate the IL-23/IL-23R/Th17 cell axis by targeting a disintegrin and metalloprotease 17 (ADAM17) in Hashimoto’s thyroiditis." (PMID 34140947, 2021).
Hepatitis B (2 papers, 2013 to 2023). "To explore the role of IL-23 on IL-17 production in hepatitis B pathogenesis, we investigated which cell type(s) adopted IL-23 signals to produce the pathogenic IL-17 by detecting the expression of IL-23R in IL-17+ cells in liver tissue." (PMID 23825942, 2013). "Recently, it was found that both Th17 cells and IL-23R expression are increased in patients with AH and Hepatitis B, respectively." (PMID 38162671, 2023). "In conclusion, the findings from this study demonstrate that the IL-23/IL-23R axis is highly activated and closely correlated with Th17 cells, liver damage and clinical phenotypes of hepatitis B patients." (PMID 23825942, 2013). "To investigate the potential effects of IL-23 on hepatitis B, we evaluated the expression of IL-23R in HBV infected liver tissues." (PMID 23825942, 2013). "Confocal microscopy revealed that IL-17 was almost completely co-localized with IL-23R in hepatitis B-infected liver tissues." (PMID 23825942, 2013). "However, in order to understand the functions of the IL-23/IL-23R axis related to liver damage caused by HBV infection, the interplay between elevated IL-23/IL-23R and IL-17 in hepatitis B patients has to be clarified." (PMID 23825942, 2013). "The significantly positive correlations that were observed between IL-23/IL-23R and IL-17 expression in patients with hepatitis B led us to investigate whether IL-23 is indispensable for HBV antigen-stimulated IL-17 production." (PMID 23825942, 2013). "When determining the expression of IL-23R in PBMCs of patients with CHB by flow cytometry (FCM) analysis, we also found that most IL-23R+ cells were IL-17+CD4+ T cells, which indicated that the circulating Th17 cells expressed a high level of IL-23R under the hepatitis B condition." (PMID 23825942, 2013).
immune deficiency (2 papers, 2018 to 2023). "In addition, the identification of the mechanism of action of the C115Y IL23R mutation could have implications for patients who have immunodeficiencies caused by this variant." (PMID 37208328, 2023).
inflammatory skin disorder (2 papers, 2009 to 2023). "Furthermore, IL-23, predominantly secreted by DCs, is known to be involved in the modulation of many cellular processes and has been associated with various inflammatory skin disorders due to its capacity to bind to the IL-23R present on the surface of DCs." (PMID 38089052, 2023).
laryngeal carcinoma (2 papers, 2021 to 2024). Carcinoma that arises from the laryngeal epithelium. "IL23R is involved in the immune-editing of laryngeal cancer cells for drug resistance and survival." (PMID 38528565, 2024).
myocardial infarct (2 papers, 2010 to 2018). "At this juncture, we can only speculate about the reasons, why we were not able to detect/reproduce a phenotype in IL-23R-Y416FΔICD signaling deficient mice after myocardial infarction." (PMID 30459442, 2018). "Surprisingly, these mice revealed that IL-23R signaling plays no role in the healing phase of myocardial infarction after ischemia/reperfusion." (PMID 30459442, 2018).
myositis (2 papers, 2018 to 2024). "In a murine autoimmune myositis model, the severity of myositis was rescued by anti-IL-23R antibodies." (PMID 39456842, 2024). "In comparison with mice treated with the control antibodies, the severity of the myositis was suppressed significantly in mice treated with the anti-IL-23R antibodies (p < 0.05)." (PMID 29615652, 2018).
nasopharyngeal carcinoma (2 papers, 2014 to 2017). A carcinoma arising from the nasopharyngeal epithelium. "Combined with our previous study of these polymorphisms in breast, lung, and nasopharyngeal cancers with diverse etiologies, our data further raises the possibility that IL-23R variant might be a common susceptibility factor for human cancer." (PMID 24586528, 2014). "One of our previous studies have demonstrated that the IL-23R rs10889677A>C SNP may alter IL-23R expression by modifying miR-let-7f binding to the 3′UTR of the IL-23R gene, thereby influence the transcription of IL-23R in vivo and in vitro in breast, lung and nasopharyngeal cancer." (PMID 24586528, 2014).
Obesity (2 papers, 2015 to 2024). Accumulation of substantial excess body fat. "Liver‐secreted Orm2 promoted thermogenesis in BAT and scWAT via p38 through binding to cell surface GP130/IL23R and administration of Orm2 ameliorated HFD‐induced obesity in vivo." (PMID 39248328, 2024). "Overall, the research identifies Orm2 as a promising therapeutic target for obesity, mediating adipose browning through the GP130/IL23R‐p38 signalling pathway." (PMID 39248328, 2024). "Notably, recombinant Orm2 but not the IL23R/GP130‐binding mutant form ameliorated HFD‐induced obesity." (PMID 39248328, 2024).
Oral squamous cell carcinoma (2 papers, 2024 to 2025). "A study utilizing a mouse oral squamous cell carcinoma (OSCC) model revealed that IL-23R+ regulatory T cells (Tregs) demonstrated lower expression of the Foxp3 transcription factor and elevated T-bet protein compared to IL-23R- Tregs." (PMID 39796684, 2024).
osteonecrosis (2 papers, 2017 to 2025). A none disease characterized by death of bone tissue due to a lack of blood supply. "Genetic mutation of alcohol-metabolizing enzyme genes has been associated with alcohol-induced osteonecrosis and polymorphism of NOS3, ABCB1 and IL23R gene are related with developing osteonecrosis." (PMID 28422712, 2017). "Some polymorphisms of the IL23R gene are associated with osteonecrosis and may be linked to preexisting pathological inflammatory conditions and immunological aspects, but they have been little studied." (PMID 41153343, 2025). "It has also been described that IL-23R rs1569922 polymorphism may play an important role in the development of osteonecrosis of the FH (ONFH), a condition that occurs in young adults whose average age varies, in the literature, between 27 and 36 years." (PMID 41153343, 2025).
pancreatic cancer (2 papers, 2013 to 2024). "We also found suggestive evidence for an association of genetically-proxied interleukin-23 receptor concentrations with pancreatic cancer risk." (PMID 38301482, 2024). "In colocalisation analysis employing conditional analysis adjusting for rs11581607, evidence of shared causal variants across interleukin-23 receptor and pancreatic cancer risk associations persisted (PPH4 = 69.8%)." (PMID 38301482, 2024).
periodontal disease (2 papers, 2020 to 2025). "In periodontal disease, IL-23R expression is upregulated on various immune cells, including T-cells and myeloid cells, contributing to the expansion of the Th17 response." (PMID 40297579, 2025).
rectal cancer (2 papers, 2015 to 2023). A primary or metastatic malignant neoplasm that affects the rectum. "To explore this possibility, we surveyed data obtained from The Cancer Genome Atlas (TCGA) to examine IL23R expression across various cancer types and found that IL23R expression was increased specifically in colon and rectal cancers when compared to other cancer types." (PMID 38375204, 2023).
schistosomiasis (2 papers, 2014 to 2017). An infectious disease caused by parasitic trematodes of the genus Schistosoma that colonize human blood vessels and release eggs that can cause granulomatous reactions leading to acute (swimmer's itch or acute schistosomiasis syndrome) or chronic disease. "This study investigated the association between five IL-23R variants and risk to schistosomiasis-associated IRIS in a Kenyan population naturally exposed to schistosomiasis." (PMID 24912586, 2014). "In conclusion, we demonstrate for the first time, in this case–control study from a high-risk Kenyan population that the non-synonymous SNP rs1884444 (His3Gln) of IL-23R gene was associated with a decreased risk of schistosomiasis-associated IRIS." (PMID 24912586, 2014). "However, the exact molecular mechanism by which IL-23 regulates Th17 cell and the associated activities of the IL-23, IL-23R, and their SNPs and susceptibility to schistosomiasis-associated IRIS are undefined and require further studies." (PMID 24912586, 2014).
Achalasia (1 paper, 2024). A disorder of esophageal motility characterized by the inability of the lower esophageal sphincter to relax during swallowing and by inadequate or lacking peristalsis in the lower half of the body of the esophagus. "Genetic risk factors within the HLA-DQ receptor, SNPs on the IL23R which regulates T cell differentiation, on PTPN22, which is a down-regulator of T-cell activation, and IL10 gene promoter were identified, emphasizing the concept of a genetically driven immune response in patients with achalasia." (PMID 39337632, 2024). "Subsequently, a panel of eleven SNPs in the IL33, IL1RL1, IL23R and IL10 genes was analyzed in an Italian cohort, using TaqMan genotyping assays, reporting significant differences in allele and genotype frequencies of the rs3939286 variant of the IL33 gene between achalasia patients and controls." (PMID 39337632, 2024).
alcohol (1 paper, 2017). "This study provides evidence for three alcohol-induced ONFH susceptibility genes (NOS3, ABCB1 and IL23R) in Chinese males and polymorphisms of them may be associated with alcohol-induced ONFH risk." (PMID 28422712, 2017).
allergic aspergillosis (1 paper, 2021). "Moreover, in experiments with RORγt-mCherry reporter mice with allergic aspergillosis, we found a significant correlation between mCherry and IL-23R expression in lung eosinophils." (PMID 34464425, 2021). "We observed IL-23R expression on eosinophils too in our models of acute and allergic aspergillosis." (PMID 34464425, 2021). "To determine whether protein expression was accompanied by active gene expression, we sorted eosinophils from the lungs of wild-type mice with allergic aspergillosis and analyzed RORγt, IL-17, and IL-23r mRNA by reverse transcriptase (RT)-PCR." (PMID 34464425, 2021).
allergic asthma (1 paper, 2020). A asthma with a basis in a pathological type I hypersensitivity reaction. "We recently reported that IL-23 was secreted from airway epithelial cells in a murine model of allergic asthma elicited by house dust mite allergen exposure and administration of IL-33, an epithelium-derived innate cytokine, following activation of IL-23R signaling." (PMID 31956268, 2020).
Alpha-thalassemia (1 paper, 2017). Alpha-thalassemia is an inherited hemoglobinopathy characterized by impaired synthesis of alpha-globin chains leading to a variable clinical picture depending on the number of affected alleles. "Using logistic regression analysis models, controlling for the confounding effects of age, sex, co-infection (HIV-1 status and bacteremia), HbAS, alpha-thalassemia, and G6PD deficiency, we determined the association between carriage of the IL-23R rs1884444 and rs7530511 haplotype constructs and SMA." (PMID 28427357, 2017).
anemia (1 paper, 2017). A reduction in the number of red blood cells, the amount of hemoglobin, and/or the volume of packed red blood cells. "In addition, due to the fact that polymorphisms may have distinct effects in different ethnic groups presenting with varied forms of severe malaria, studies across various ethnic groups are warranted to decipher fully the impact of IL-23R variation on susceptibility to severe malaria anemia." (PMID 28427357, 2017).
autism (1 paper, 2024). Persistent deficits in social interaction and communication and interaction as well as a markedly restricted repertoire of activity and interest as well as repetitive patterns of behavior. "Six genes were significantly differentially expressed between autism likelihood (social communication) groups: CYSLTR2, NOX1, C1QA, CXCL10, C8A, IL23R (all up-regulated, p < 0.05)." (PMID 39247132, 2024).
autoimmune hepatitis (1 paper, 2021). Hepatitis caused by autoantibodies. "In this autoimmune hepatitis model, splenectomy prior disease induction increased the amount of IL-17, IL-23R and caspase-3 in the sera of mice with experimental murine autoimmune hepatitis." (PMID 33435354, 2021).
bladder urothelial carcinoma (1 paper, 2022). "Specifically, the rs-1884444 G/T variant of IL-23R was strongly linked to a decreased risk of bladder urothelial carcinoma." (PMID 36140470, 2022). "Deregulation of the IL-23/IL-17 pathway is associated with bladder urothelial carcinoma risk because IL-23R is a critical component of the T-helper 17 cell-mediated inflammatory process that orchestrates inflammation, thereby promoting tumor growth." (PMID 36140470, 2022).
celiac disease (1 paper, 2009). An autoimmune genetic disorder with an unknown pattern of inheritance that primarily affects the digestive tract. "Hence, the IL12A association and the proximity of IL12RB2 to IL23R (which appears linked to celiac disease), suggest that the genes of the IL12 pathway are particularly interesting to investigate in future genetic studies of celiac disease." (PMID 19175939, 2009). "But perhaps the most interesting novel finding is that of linkage of the IL23R region to celiac disease." (PMID 19175939, 2009). "Variants in the LD block upstream of IL23R or in the downstream LD block covering IL12RB2, may explain the linkage to celiac disease in the Finnish population." (PMID 19175939, 2009). "It remains to be elucidated whether IL23R, IL12RB2 or another gene at 1p31 confers risk to celiac disease." (PMID 19175939, 2009). "Therefore, it is possible that the IL23R region is linked to celiac disease in the Finnish population but not the Hungarian." (PMID 19175939, 2009). "The Hungarian pedigrees with celiac disease showed neither significant linkage to the SNPs in the IL23R region (lod = 0.4, p = 0.08, 132 informative families) nor significant association (data not shown)." (PMID 19175939, 2009). "Importantly, this is the first report of linkage of the IL23R region to celiac disease, a chronic inflammatory condition in which IL23R has not been previously implicated." (PMID 19175939, 2009).
Chronic colitis (1 paper, 2010). A chronic inflammatory disease of the large intestine (colon, cecum and rectum). "IL-23 has been shown to play a key role in both innate and T cell mediated chronic colitis in mouse models and IL23R has been identified as a risk gene in IBDs." (PMID 20732640, 2010). "Here, we have utilized Il23r−/− mice to assess the role of IL-23R signaling in T cells in the development of chronic colitis." (PMID 20732640, 2010).
chronic hepatitis (1 paper, 2013). An active inflammatory process affecting the liver for more than six months. "Here, we describe our investigations into the role of intrahepatic IL-23/IL-23R signaling during development of lethal or chronic hepatitis." (PMID 23825942, 2013).
chronic hepatitis B (1 paper, 2022). "Several studies have confirmed that several SNPs of the IL-23R gene are associated with susceptibility to infectious disease, such as HBeAg-positive chronic hepatitis B." (PMID 36483566, 2022).
coronary artery disease (1 paper, 2020). "An IL-23R polymorphism was observed to be related to coronary artery disease, and the IL-23R rs6682925T/C polymorphism may independently relate to the presence of coronary artery disease." (PMID 32194399, 2020).
dry eye (1 paper, 2024). "Clinical cases of dry eye have also shown increased expression of the IL-23/Th17 axis, leading to higher levels of IL-6, IL-23R, TGF-β2, and the transcription factor RoRγt." (PMID 38898418, 2024).
emphysema (1 paper, 2016). "Using IL-23R antibody for labeling the cells from BAL, we observed that IL-23R is expressed in a population of lymphocytes present in HIV1− and HIV1+ smokers with early emphysema." (PMID 27446965, 2016).
giant-cell arteritis (1 paper, 2021). "In this group, we found the IL23R, recently found increased in giant-cell arteritis (GCA) lesions and recognized to play central role in stimulating inflammatory and proliferative pathways relevant to GCA pathogenesis." (PMID 33525692, 2021).
glioblastoma (1 paper, 2021). The most malignant astrocytic tumor (WHO grade IV). "However, the role of IL-23R in glioblastoma remains unknown." (PMID 34412691, 2021).